WNT5A (Wnt family member 5A)
Diseases named in the same sentence as WNT5A in open-access papers (continued):
Sharing a sentence is not in itself a finding about the gene and the disease.
spondyloarthritis (2 papers, 2019 to 2022). "In contrast to PsO, in which Wnt5a is overexpressed, there has been no report of Wnt5a expression in PsA tissues, although Wnt5a is expressed locally in the joints of spondyloarthritis patients, which include PsA patients." (PMID 31313518, 2019).
steatosis (2 papers, 2021 to 2022). Increased lipid within the cytoplasm of cells. "Still, the increased expression of WNT5A in adipose tissue would make sense in firsts stages of steatosis, since in subjects with MO, there is an adipose tissue overproliferation mediated by WNT5A." (PMID 36077270, 2022). "Since we reported a peak of SFRP5 and WNT5A expressions in the SS mild stage in VAT samples, we decided to study the involvement of these genes focusing on the steatosis grades, regardless of inflammation or ballooning presence, in the analyzed cohort." (PMID 36077270, 2022).
T-cell leukemia (2 papers, 2017 to 2021). A malignant disease of the T-lymphocytes in the bone marrow, thymus, and/or blood. "However, Wnt5a has also been shown to increase survival in B-cell precursor acute lymphoblastic leukemic Nalm-16 cells, and promotes proliferation and migration in HTLV-1-infected adult T-cell leukemia cells." (PMID 28380463, 2017).
tendinopathy (2 papers, 2011 to 2025). "Additionally, tendinopathy tissue showed differential expression of other WNT pathway genes, including increased expression of CTNNB (1.5-fold), WNT5a (2.7-fold), and FZD1 (1.7-fold) and decreased expression of LRP5 (0.59-fold) and FRZB (0.35-fold)." (PMID 21539748, 2011).
Abdominal obesity (1 paper, 2017). Excessive fat around the stomach and abdomen. "In agreement with previous studies by our group and others, we observed a correlation between WNT5A expression in VAT and waist-to-hip ratio, an anthropometric indicator of abdominal obesity." (PMID 29229927, 2017).
acute liver failure (1 paper, 2023). Rapid deterioration of liver function causing encephalopathy and coagulopathy. "Recently, we investigated the prognostic role of serum Wnt5a in ACHBLF patients and explored the underlying mechanism of Wnt5a contributing to acute liver failure with a mouse model." (PMID 38062395, 2023). "Furthermore, we demonstrated that Wnt5a expression was enhanced in a mouse model of acute liver failure." (PMID 38062395, 2023).
amyloid (1 paper, 2015). "Additionally, the in vivo activation of Wnt signaling, with a mimetic peptide of Wnt-5a, rescues memory loss and improves synaptic dysfunction in APP/PS1-transgenic mice, a model the amyloid pathology of AD." (PMID 26124704, 2015).
ankyloglossia (1 paper, 2023). A developmental abnormality in which the bottom of the tongue is attached to the floor of the mouth. "Moreover, proper levels of Wnt5a in the mesenchyme are essential for tongue outgrowth, as the Wnt5a knockout mice presented with a shorter tongue with ankyloglossia." (PMID 37680190, 2023).
aortic valve calcification (1 paper, 2024). "Therefore, our study provides novel insights into the molecular mechanism regulating Wnt5a/Ca2+ in the pathogenesis of CAVD, targeting ECH1 may prove of therapeutic potential to aortic valve calcification." (PMID 38946717, 2024).
arteriosclerosis (1 paper, 2019). A vascular disorder characterized by thickening and hardening of the walls of the arteries. "In several studies, it has been reported that during arteriosclerosis, macrophages regulate the production of inflammatory cytokines through Wnt5a expression." (PMID 31698687, 2019).
atopic dermatitis (1 paper, 2024). "We found that WNT5A+/IL24+ signature genes were absent from healthy skin, weakly expressed in atopic dermatitis, but readily detectable in prurigo nodularis lesions." (PMID 38291032, 2024).
bone sarcoma (1 paper, 2015). A sarcoma that arises from the bone. "In contrast, among noncanonical Wnt ligands, the expression of Wnt5a, Wnt5b and Wnt16 was either decreased or lost in bone sarcoma cells; however, Wnt6, Wnt7b, and Wnt11 were remarkably increased in bone sarcoma cells." (PMID 25999350, 2015).
Charcot arthropathy (1 paper, 2022). "In this study, we could show a significant downregulation of WNT3A and WNT5A in patients suffering from T2DM induced Charcot arthropathy with the need of surgical treatment." (PMID 35436882, 2022). "In T2DM patients who had developed Charcot arthropathy WNT3A and WNT5A gene expression was down-regulated by 89 and 58% compared to healthy controls (p < 0.0001)." (PMID 35436882, 2022). "For the first time significant changes in gene expression of the Wnt signaling pathway – namely WNT3A, WNT5A, TCF7L2 and osteocalcin- in the bone of patients suffering from T2DM and following Charcot arthropathy could be shown." (PMID 35436882, 2022).
cholangiocarcinoma (1 paper, 2017). A carcinoma that arises from the intrahepatic biliary tree (intrahepatic cholangiocarcinoma) or from the junction, or adjacent to the junction, of the right and left hepatic ducts (hilar cholangiocarcinoma). "CXCL12/CXCR4 signaling promotes cholangiocarcinoma progression and metastasis via the canonical Wnt pathway, and Wnt5a is a critical mediator of human and murine T cell CXCL12/CXCR4 signaling and migration." (PMID 28380463, 2017).
choroidal melanoma (1 paper, 2021). Malignant tumor of melanocytes of the choroid. "Collectively, our results suggested that ART inhibited angiogenesis and VM formation of choroidal melanoma likely by regulating the Wnt5a/CaMKII signaling pathway." (PMID 34476217, 2021).
chronic asthma (1 paper, 2020). An asthma that is characterized by the development of persistent airway inflammation and recurrent attacks of breathlessness and wheezing, which vary in severity and frequency. "Accordingly, we observed increased IL31 levels in the chronic asthma model, which were exaggerated in WNT5A transgenic mice in response to allergen exposure." (PMID 32317758, 2020).
chronic hepatitis B virus infection (1 paper, 2023). Chronic form of hepatitis B infection. "Wnt5a mRNA levels in peripheral blood mononuclear cells (PBMCs) were analyzed in 31 acute-on-chronic hepatitis B liver failure (ACHBLF) patients, 82 chronic hepatitis B (CHB) patients, and 20 healthy controls using quantitative real-time polymerase chain reaction." (PMID 38062395, 2023).
chronic myeloid leukaemia (1 paper, 2019). "Mice heterozygous for Wnt5a develop chronic myeloid leukaemia or B-cell disorders, while the analysis of 10 AML samples revealed deletion of the WNT5A gene and/or loss of WNT5A expression in a fraction of samples." (PMID 31703382, 2019).
cleft lip (1 paper, 2024). Congenital defect in the upper lip where the maxillary prominence fails to merge with the merged medial nasal prominences. "WNT5A rs566926 was significantly associated with an increased risk of NSCL±P, particularly due to a strong association with non-syndromic cleft lip only (NSCLO), in which the C allele increased the risk by 32% (OR: 1.32, 95% CI: 1.04–1.67, p=0.01)." (PMID 38359266, 2024).
cognitive decline (1 paper, 2017). "This is consistent with studies suggesting that upregulation of Wnt5a signaling is involved in the cognitive decline associated with aging and also with the physiopathology of AD." (PMID 29202785, 2017).
Cognitive impairment (1 paper, 2023). Abnormal cognition is characterized by deficits in thinking, reasoning, or remembering. "Another report mentions that Wnt5a alters neuron cholesterol metabolism and alleviates cognitive impairment in a progressive PD model." (PMID 36680208, 2023).
colorectal adenocarcinoma (1 paper, 2022). The most common type of colorectal carcinoma. "Moreover, expression of the majority of the genes (CACNA1H, COL1A1, COL11A1, FZD8, NGFR, SFRP2, WNT2B, and WNT5A) was associated with the ‘mesenchymal’ CMS group 4 in the TCGA (The Cancer Genome Atlas) Colorectal Adenocarcinoma dataset." (PMID 35892888, 2022).
congenital heart malformation (1 paper, 2015). A disease that has its basis in the disruption of heart development. "No study to date has comprehensively characterized the WNT5A regulatory variants in patients with congenital heart malformations (CHMs)." (PMID 26278011, 2015).
congestive heart failure (1 paper, 2025). Failure of the heart to pump a sufficient amount of blood to meet the needs of the body tissues, resulting in tissue congestion and edema. "IGFBP-2 and WNT5A were elevated in subclinical disease, whereas IL-18 and WNT5A increases were more pronounced in cats with congestive heart failure (CHF)." (PMID 41487485, 2025).
coronary artery disease (1 paper, 2022). "In patients undergoing cardiac surgery, elevated basal WNT-5a values in the serum and epicardial adipose tissue were associated with the presence of coronary artery disease." (PMID 36440011, 2022).
Co‐infection (1 paper, 2020). "Co‐infection with both AdTGFB and AdWNT5A resulted in a similar increase in WNT5A (P = .05)." (PMID 32052562, 2020).
craniopharyngioma (1 paper, 2022). A benign, partly cystic, epithelial tumor of the sellar region, presumably derived from Rathke pouch epithelium. "Similarly, the association between pathways in cancer and ACPs has not been reported, but the three most significant key genes (CDH1, WNT5A, and SHH) have been closely/positively associated with craniopharyngioma." (PMID 36387067, 2022).
Crohn disease (1 paper, 2015). A gastrointestinal disorder characterized by chronic inflammation involving all layers of the intestinal wall, noncaseating granulomas affecting the intestinal wall and regional lymph nodes, and transmural fibrosis. "Wnt5a expression was then examined in the colon from Crohn’s disease (9 cases) and ulcerative colitis (10 cases) patients." (PMID 26030277, 2015). "In addition, our human studies show that Wnt5a was clearly observed in vimentin-positive cells, but not macrophages, in the ulcer lesions of patients with ulcerative colitis and Crohn’s diseases." (PMID 26030277, 2015).
cytomegalovirus infection (1 paper, 2020). A herpesvirus infection caused by Cytomegalovirus. "Cytomegalovirus infection also modulates the expression of noncanonical Wnt receptor tyrosine kinase-like orphan receptor 2 (ROR2) to alter Wnt5a-mediated signaling and inhibit trophoblast motility." (PMID 33374185, 2020).
E. coli infections (1 paper, 2020). "Since phagosomes control the fate of internalized bacteria, we examined if the respective phagosome compositions associated with pathogenic (K1) and non-pathogenic (K12-MG1655) E. coli infections in Wnt5A activated macrophages feature the observed differences in actin assembly." (PMID 33664738, 2020).
endometriosis (1 paper, 2017). The growth of functional endometrial tissue in anatomic sites outside the uterine body. "In human endometrium, WNT5A, encoding a non-canonical WNT signaling protein, acts as pro-survival protein during decidualization, so this gene is a compelling candidate for a functional role in endometriosis." (PMID 28125717, 2017).
Endotoxemia (1 paper, 2015). "In the present study, we measured the key components of Wnt5a signaling pathway in the lung of endotoxemia rats to gain further insights into Wnt5a/Fzd5/CaMKII biology." (PMID 26218875, 2015).
epithelial ovarian tumor (1 paper, 2016). "However, one study reported that Wnt5A supresses epithelial ovarian tumor formation by promoting surface epithelial cell senecsence." (PMID 28536612, 2016).
frontotemporal lobar degeneration (1 paper, 2022). "In addition, GRN haploinsufficiency detectable in patients with frontotemporal lobar degeneration is associated with Wnt5a signaling in neuronal cells but no connection with RYK has been established." (PMID 36471440, 2022).
gingivitis (1 paper, 2021). A disorder involving inflammation of the gums; may affect surrounding and supporting structures of the teeth. "This can be attributed to the increased variability in WNT-5a production among individuals and the low number of individuals in the gingivitis patient group." (PMID 34440994, 2021). "Considering the literature, this is the first investigation to address the total protein amounts of SOST and WNT-5a in gingivitis sites." (PMID 34440994, 2021). "The total amounts of Sclerostin and WNT-5a in GCF samples of individuals with a healthy periodontium, gingivitis and generalized periodontitis were evaluated in this study." (PMID 34440994, 2021).
glaucoma (1 paper, 2019). Increased pressure in the eyeball due to obstruction of the outflow of aqueous humor. "A tissue-specific inducible Wnt5a transgenic mouse line would be able to maintain long term Wnt5a expression and eventually may be helpful in determining if Wnt5a can also cause glaucoma and the relationship between glaucoma and PEX syndrome." (PMID 30840655, 2019). "To test if Wnt5a alone can induce glaucoma, we injected Adenovirus-Wnt5a into the anterior chamber of the mouse eyes." (PMID 30840655, 2019). "The Wnt5a expression only lasts about three weeks after injection, while many PEX-associated features, including glaucoma development, may take much longer to develop." (PMID 30840655, 2019).
glomerulosclerosis (1 paper, 2016). A hardening of the kidney glomerulus caused by scarring of the blood vessels. "The BM defects lead also later to compromised kidney filter in the adult Wnt5a deficient mouse resembling the glomerulosclerosis condition." (PMID 26794322, 2016). "The anomalies in the glomerulus were notable worse in the Wnt5a+/-;P4ha1+/- adult mice being in line with a severe glomerulosclerosis condition." (PMID 26794322, 2016).
Hodgkins lymphoma (1 paper, 2023). A heterogeneous group of malignant lymphoid neoplasms of B-cell origin characterized histologically by the presence of Hodgkin and Reed-Sternberg (HRS) cells in the vast majority of cases. "Other Wnt genes have been implicated in haematopoietic malignancies, such as WNT5A, which has been identified as a tumour suppressor that inhibits B-cell proliferation and is a motility factor in Hodgkin’s lymphoma cells." (PMID 37756103, 2023).
hydronephrosis (1 paper, 2016). Collection of urine in the renal pelvis that results in dilatation of the renal pelvis and calyces. "Of the genes identified in this screen to cause duplex kidneys or hydronephrosis, only Wnt5a was previously shown to cause renal–urinary tract anomalies in humans." (PMID 27002738, 2016).
infarction (1 paper, 2023). A localised pathological necrosis of tissue resulting from obstruction of the blood supply usually by a thrombus, an embolus, or vascular torsion. "Through direct effects on cardiac fibroblast migration and activation in the infarcted tissue, CTHRC1 enhances post-infarction wound repair and reduces cardiac rupture as well as the mortality rate via selectively activating non-canonical WNT5A-PCP signaling pathway." (PMID 36923925, 2023). "Importantly, rWNT5A protein treatment could reverse Cthrc1 deficiency-induced post-MI cardiac rupture, which further supports that CTHRC1 promoted post-infarction cardiac repair via selectively activating non-canonical WNT5A-PCP signaling pathway other than canonical WNT3A-β-catenin signaling axis." (PMID 36923925, 2023).
inflammatory breast carcinoma (1 paper, 2023). An advanced, invasive breast adenocarcinoma characterized by the presence of distinct changes in the overlying skin. "The AhR signaling pathway elevates the expression of β-catenin and of Wnt5a/b in the tumor tissue of patients with inflammatory breast cancer (IBC) that overexpresses AhR and its target gene/protein CYP1B1." (PMID 37232717, 2023).
influenza (1 paper, 2024). An acute viral infection of the respiratory tract, occurring in isolated cases, in epidemics, or in pandemics; it is caused by serologically different strains of viruses (influenzaviruses) designated A, B, and C, has a 3-day incubation period, and usually lasts for 3 to 10 days. "It has been shown that following influenza-induced lung injury in vivo, Wnt5a is secreted from fibroblasts to stimulate induction of epithelial progenitor cells." (PMID 38476262, 2024).
intervertebral disc degeneration (1 paper, 2020). "Li and colleagues also found that Wnt5a inhibited inflammation-driven intervertebral disc degeneration through negative feedback regulation of NF-kB." (PMID 32228612, 2020).
Kidney Damage (1 paper, 2021). "The regulation of WNT5A in diverse inflammatory diseases is well known, but its participation in PE-related kidney damage has rarely been studied." (PMID 33790866, 2021).
leukoplakia (1 paper, 2007). A white patch or plaque on a mucous membrane that cannot be characterized clinically or pathologically as any other disease. "No signal was detectable with antibodies against Wnt1 and Wnt7a in normal and leukoplakia epithelia, whereas Wnt5a signal was ubiquitously detectable in normal oral epithelium, leukoplakia, and in OSCC (data not shown)." (PMID 17922924, 2007).
lipoma (1 paper, 2018). A benign, usually painless, well-circumscribed lipomatous tumor composed of adipose tissue. "Three genes had differential H3K4me3 and H3K27me3 peaks, Trp63 (transformation related protein 63); Wnt5a (wingless-type MMTV integration site family, member 5A); and Lhfpl3 (lipoma HMGIC fusion partner-like 3)." (PMID 30214456, 2018).
lymphangioma (1 paper, 2021). A benign lesion composed of dilated lymphatic channels. "Dermal lymphatic dysplasia occurred in mice knocked out for Wnt5a and a high level of Wnt5a expression was detected in LM-LECs, indicating that Wnt5a may play an important role in lymphangioma formation." (PMID 34976885, 2021).
lymphoid leukemia (1 paper, 2020). A malignant lymphocytic neoplasm of B-cell or T-cell lineage involving primarily the bone marrow and the peripheral blood. "In lymphoid leukemia, there is evidence that Wnt5a induces ROR1/ROR2 hetero-oligomerization and Rac1 activation, and that Wnt5a presence might offer a survival advantage." (PMID 32751131, 2020).
Macrocephaly (1 paper, 2024). Occipitofrontal (head) circumference greater than 97th centile compared to appropriate, age matched, sex-matched normal standards. "From these genes, four are associated either with microcephaly (CUL3 [MIM: 603136]) or macrocephaly (CDH2 [MIM: 114020], GLI3 [MIM: 165240], and WNT5A [MIM: 164975])." (PMID 39168120, 2024).
medulloblastoma (1 paper, 2017). A malignant, invasive embryonal neoplasm arising from the cerebellum. "As our results confirms the role of Wnt5a in regulating proliferation of VZ progenitors and RL progenitors during early development it is possible that Wnt5a signaling might be one of the important signaling that could drive medulloblastoma tumorigenesis." (PMID 28205531, 2017). "Further Wnt5a, a classic non-canonical Wnt ligand has been shown to be expressed highly in medulloblastoma tumor samples but its role in cerebellar development remains obscure." (PMID 28205531, 2017).
meningioma (1 paper, 2023). A generally slow growing tumor attached to the dura mater. "NMNA2 is known to promote cancer cell survival, whereas WNT5A is a member of the oncogenic WNT protein family and is expressed in meningioma and many other tumors." (PMID 37368072, 2023).
mental disorder (1 paper, 2018). A disease that has its basis in the disruption of mental process. "Our findings could suggest that drugs blocking the non-canonical Wnt Ca pathway (e.g., WNT5A antagonists) could have a role in the treatment of severe mental disorders and warrants further investigation." (PMID 29507296, 2018).
Micrognathia (1 paper, 2025). Developmental hypoplasia of the mandible. "Conditional Wnt5a GOF, viral Wnt5a overexpression, viral missense variant-containing Wnt5a overexpression, and global Wnt5a knockout cause micrognathia, but conditional Wnt5a LOF does not." (PMID 40777421, 2025).
minimal change disease (1 paper, 2021). "To examine whether Wnt5a signaling was involved in DN, we performed Wnt5a immunostaining on kidney biopsy samples of patients with DN and minimal change disease (MCD) and on normal kidney sections of nephrectomy samples." (PMID 33462195, 2021).